TRIM69 (tripartite motif containing 69)
Description:
E3 ubiquitin ligase that plays an important role in antiviral immunity by restricting different viral infections including dengue virus or vesicular stomatitis indiana virus. Ubiquitinates viral proteins such as dengue virus NS3 thereby limiting infection. In addition, acts as a key mediator of type I interferon induced microtubule stabilization by directly associating to microtubules independently of its E3 ligase activity. Regulates centrosome dynamics and mitotic progression by ubiquitinating STK3/MST2; leading to its redistribution to the perinuclear cytoskeleton and subsequent phosphorylation by PLK1.
Synonyms: RNF36; HSD-34; HSD34; Trif; TRIMLESS
Tractability: No criterion of Open Targets' tractability assessment is met for any kind of drug.
Gene: Protein-coding gene on chromosome 15 (44,728,988 to 44,767,829, forward strand). Ensembl gene ENSG00000185880.
Subcellular location: Cytoplasm; Nucleus; Nucleus speckle; Cytoplasm, cytoskeleton, microtubule organizing center, centrosome
Pathways (Reactome):
Immune System: Antigen processing: Ubiquitination & Proteasome degradation
Gene Ontology:
Molecular function: protein binding; ubiquitin protein ligase activity; ubiquitin-protein transferase activity
Biological process: positive regulation of cGAS/STING signaling pathway; protein K63-linked ubiquitination; protein localization to centrosome; innate immune response; protein ubiquitination
Cellular component: centrosome; cytoplasm; nuclear speck; nucleus; cytosol
Genetic constraint (gnomAD): Loss-of-function variants: 33 observed, 45.05 expected, observed/expected ratio (o/e) 0.73, 90% interval 0.55 to 0.98. The upper end of that interval is the gene's LOEUF score, 0.98, which puts it in group 4 of 6, group 1 being the genes least tolerant of losing a copy. Missense variants: 575 observed, 583.48 expected, observed/expected ratio (o/e) 0.99, 90% interval 0.92 to 1.06. Synonymous variants: 201 observed, 215.7 expected, observed/expected ratio (o/e) 0.93, 90% interval 0.83 to 1.05.
Homologues: Orthologues: chimpanzee TRIM69 (98% identical), macaque TRIM69 (96% identical), rabbit TRIM69 (88% identical), dog TRIM69 (87% identical), pig TRIM69 (87% identical), rat Trim69 (79% identical), mouse Trim69 (79% identical), guinea pig TRIM69 (75% identical), tropical clawed frog trim69 (41% identical). Paralogues in human: TRIM39 (30% identical), TRIM7 (30% identical), TRIM26 (28% identical), TRIM21 (28% identical), TRIM27 (28% identical), TRIML1 (27% identical), TRIM4 (27% identical), TRIM41 (27% identical), TRIM58 (27% identical), TRIM11 (26% identical), TRIM50 (25% identical), TRIM10 (25% identical), and 68 more.
Diseases named in the same sentence as TRIM69 in open-access papers:
TRIM69 is named in the same sentence as 20 diseases in open-access papers, as found by Europe PMC text mining. Sharing a sentence is not in itself a finding about the gene and the disease. The quoted sentences say what the papers report.
viral infection (7 papers, 2018 to 2025). "Notably, although TRIM69 associates with acetylated microtubules, microtubule acetylation is not required for its restriction activity, suggesting an independent role for TRIM69 in both inducing microtubule acetylation and restricting viral infections." (PMID 39804091, 2025). "The findings presented in this study shed light on the role of microtubule acetylation on HIV-1 infection and TRIM69-mediated inhibition of viral infection." (PMID 39804091, 2025). "As a potent inhibitor of vesicular stomatitis virus (VSV) infection, TRIM69 regulates the innate immune suppression of a range of viral infections." (PMID 37653392, 2023). "It is therefore possible that TRIM69 inhibits viral infection by interfering with the ability of viruses to exploit microtubule trafficking during infection, although future studies are required to test this hypothesis." (PMID 39804091, 2025). "For example, G2/I2 showed hyper-editing of type 1 interferon (IFN) receptors (IFNAR1 and IFNAR2), type 1 IFN-stimulated genes (ISGs) (e.g., EIF2AK2, DDX58/RIG-1, MAVS, TRIM56, and TRIM69) and genes involved in immune responses to viral infection (EIF2AK2, DDX58/RIG-1, MAVS, CASP8, CYCS, and HMGB1)." (PMID 35406793, 2022). "Thus, our data point to the fact that TRIM69 may drive an antiviral response that makes use of MTs as a weapon against viral infection." (PMID 39205302, 2024). "Contrastingly, numerous C/II and C/III members execute elevated/robust basal levels of expression and acquire an impulse of upregulation upon virus-infection (e.g. NFKBIZ), while a few establish minimal basal levels followed by slight upregulation e.g. TRIM69." (PMID 40131776, 2025). "Yet, evidence gathered through the literature indicates that TRIM-MAPs bear a high potential to alter viral infection, either indirectly by modulating IFN responses or more directly by modulating MT dynamics, as highlighted in our results with TRIM69." (PMID 39205302, 2024). "Taken together, these data further confirmed that TRIM69 is an ISG induced by type I IFN and virus infection." (PMID 30142214, 2018). "The identification of TRIM69 as the first member of the TRIM family that reorganizes MTs, inducing broad viral inhibition, highlights the fact that the cell bears the ability to exploit its MT to fight off viral infections." (PMID 39205302, 2024). "In line with this, we also found that TRIM69 did not influence other virus infection, such as H1N1 or HSV-1." (PMID 30142214, 2018). "A previous report identified that TRIM69 is induced in peripheral blood cells upon type I IFN stimulation, here we show that TRIM69 is also upregulated in 293T, HUVEC, and HFF cells by IFN-β stimulation or virus infection, and has antiviral properties against DENV infection." (PMID 30142214, 2018).
hepatocellular carcinoma (2 papers, 2024 to 2025). A malignant tumor that arises from hepatocytes. "This interference disrupts the TRIM69-mediated degradation of FSP1 protein in hepatocellular carcinoma." (PMID 39881208, 2025). "A previous study showed that lncFAL stabilized by HDLBP, an important transporter that protects cells from overaccumulation of cholesterol, inhibits ferroptosis vulnerability by diminishing Trim69-dependent FSP1 degradation in hepatocellular carcinoma." (PMID 38191842, 2024).
HIV-1 infection (2 papers, 2024 to 2025). The type species of lentivirus and the etiologic agent of acquired immunodeficiency syndrome (AIDS). "This demonstrates that TRIM69 inhibits HIV-1 infection prior to the completion of reverse transcription and nuclear import." (PMID 39804091, 2025). "In this study, we directly target the enzyme responsible for microtubule acetylation to delineate its role in both HIV-1 infection and TRIM69-mediated restriction." (PMID 39804091, 2025). "Recent investigations have uncovered a relationship between TRIM69 and acetylated microtubules, with a recent study providing evidence that TRIM69 induces microtubule acetylation in the context of inhibiting HIV-1 infection." (PMID 39804091, 2025). "In these cells, HIV-1 infection was still potently inhibited following induction of TRIM69 expression, demonstrating that TRIM69-mediated restriction of HIV-1 operates independently of its capacity to induce acetylated microtubule formation." (PMID 39804091, 2025). "To determine if microtubule acetylation is required for TRIM69-mediated inhibition of HIV-1 infection, we established a doxycycline-inducible TRIM69 overexpression system within THP-1 cells." (PMID 39804091, 2025). "When challenged with HIV-1, we observed that increased TRIM69 expression led to a potent inhibition of HIV-1 infection." (PMID 39804091, 2025). "A key limitation of this study is the narrow focus on microtubule acetylation as the primary post-translational modification examined in the context of HIV-1 infection and TRIM69-mediated restriction." (PMID 39804091, 2025). "The goal of this study was to determine the role of microtubule acetylation in both HIV-1 infection and TRIM69-mediated restriction." (PMID 39804091, 2025). "It has recently been reported that TRIM69 expression leads to an increase in microtubule acetylation, suggesting that the mechanism by which TRIM69 can inhibit HIV-1 infection may be related to microtubule acetylation." (PMID 39804091, 2025). "We also examined the ability of TRIM69 to inhibit HIV-1 infection in the context of αTAT1 knockout." (PMID 39804091, 2025). "To more definitively understand the role of microtubule acetylation on HIV-1 infection and in TRIM69-mediated HIV-1 restriction, we examined both HIV-1 infection and TRIM69-mediated restriction of HIV-1 in cells lacking αTAT1, the acetyltransferase responsible for microtubule acetylation." (PMID 39804091, 2025). "However, we found that TRIM69 was able to potently restrict HIV-1 infection even when microtubule acetylation was prevented by αTAT1 KO." (PMID 39804091, 2025). "Similarly, a previous study characterizing the antiviral activity of TRIM69 observed inhibition of HIV-1 and microtubule acetylation induced by HIV-1 infection, suggesting that the mechanism of TRIM69 restriction may be related to its ability to induce microtubule acetylation." (PMID 39804091, 2025). "While we observed no direct change in both polyglutamylation or detyrosination of α-tubulin following αTAT1 knockout and HIV-1 infection, our study did not specifically perturb these pathways to assess their role in HIV-1 infection or TRIM69 restriction." (PMID 39804091, 2025).
breast carcinoma (1 paper, 2023). "In our analyses of TCGA data, we unexpectedly noticed that expression of the TRIM69 mRNA in basal breast cancers was very strongly associated with gene signatures for centrosome amplification (CA20), aneuploidy, and Homologous Recombination Deficiency (HRD)." (PMID 37739411, 2023). "We ectopically expressed HA-tagged versions of TRIM69A and TRIM69B in MDA-MB-231 breast cancer and in H1299 lung adenocarcinoma cells using adenoviral vectors, then determined subcellular distribution of the two TRIM69 variants using biochemical fractionation and immunoblotting." (PMID 37739411, 2023). "The molecular and biochemical roles we have defined for TRIM69A in centrosome function fully explain why high expression of TRIM69 mRNA is correlated so highly with the CA20 gene signature in basal breast cancers." (PMID 37739411, 2023). "High-level expression of TRIM69 in basal breast cancers may represent an adaptive mechanism for tolerance of spindle multipolarity." (PMID 37739411, 2023).
colon adenocarcinoma (1 paper, 2023). "The present study examined the correlation between TRIM69 expression and colon adenocarcinoma (COAD)." (PMID 37653392, 2023).
colon cancer (1 paper, 2023). "TRIM69 expression also correlated with the pathologic stage and M category of COAD, suggesting that TRIM69 may serve as a marker of metastasis in COAD and potentially be a new colon cancer suppressor." (PMID 37653392, 2023).
colorectal cancer (1 paper, 2023). A primary or metastatic malignant neoplasm that affects the colon or rectum. "Several proteins in the tripartite-motif (TRIM) family are associated with the development of colorectal cancer (CRC), but research on the role of TRIM69 was lacking." (PMID 37653392, 2023).
heart failure (1 paper, 2022). Inability of the heart to pump blood at an adequate rate to meet tissue metabolic requirements. "They used robust rank aggregation to derive an integrative transomic score for each annotated gene associated with a heart failure trait, TRIM69 for incident HF with reduced ejection fraction." (PMID 37342178, 2022). "Significantly downregulated DEGs TRIM69 has been affirmed that is associated with heart failure." (PMID 37342178, 2022).
lung carcinoma (1 paper, 2023). "TRIM69 ablation in H1299 lung cancer cells (which harbor supernumerary centrosomes) also led to reduced clonogenic survival." (PMID 37739411, 2023).
myocardial infarction (1 paper, 2024). Gross necrosis of the myocardium, as a result of interruption of the blood supply to the area, as in coronary thrombosis. "In short-term hypoxia, we also observed increased expression of E3 ubiquitin-protein ligase TRIM69, which is known to increase in myocardial infarction and is most likely involved in protein homeostasis." (PMID 39050708, 2024).
non-small cell lung carcinoma (1 paper, 2023). A group of at least three distinct histological types of lung cancer, including non-small cell squamous cell carcinoma, adenocarcinoma, and large cell carcinoma. "A study of non-small cell lung cancer (NSCLC) demonstrated that TRIM69 is associated with spindle poles and promotes centrosome clustering, which is essential for the formation of bipolar spindles, and that mitotic arrest caused by silencing TRIM69 inhibits tumor growth in vivo." (PMID 37653392, 2023).
pancreatic adenocarcinoma (1 paper, 2023). "The pan-cancer survey of distinct tumor types from patients revealed that TRIM69 was recurrently upregulated in nearly all tumors including pancreatic adenocarcinoma (PAAD), which also contained much higher levels of Ctnnb1 and Id2 than the normal controls." (PMID 36741265, 2023).
cancer (5 papers, 2023 to 2024). A tumor composed of atypical neoplastic, often pleomorphic cells that invade other tissues. "In conclusion, the present study showed that TRIM69 was significantly downregulated in COAD compared to non-cancer tissues, and the expression level of TRIM69 was associated with pathologic stage and metastasis." (PMID 37653392, 2023). "In a preliminary analysis of TCGA data, we identified an association between the E3 ubiquitin ligase TRIM69 and centrosome amplification in cancer." (PMID 37739411, 2023). "From our findings that TRIM69 expression was significantly reduced in COAD compared with non-cancer tissues and associated with pathologic stage and metastasis, we conclude that increasing TRIM69 expression and/or activity may help to improve therapeutic outcomes." (PMID 37653392, 2023). "Similar to TRIM69, other MT bundling and centrosome-clustering proteins are also typically overexpressed in cancer." (PMID 37739411, 2023). "Our work identifies new cancer-relevant mitotic mechanisms for TRIM69, thereby expanding our understanding of biological roles of the TRIM family members." (PMID 37739411, 2023). "From this analysis, lower expression of TRIM69 was detected in COAD tissues than in non-cancer tissues by RT-qPCR and immunohistochemistry." (PMID 37653392, 2023). "Gene Set Cancer Analysis (GSCA) was applied to analyze the sensitivity of tumor cells to different anti-cancer drugs according to the level of TRIM69 expression." (PMID 37653392, 2023). "In addition, TRIM69-ablation in cancer cells leads to centrosome scattering and chromosome segregation defects." (PMID 39349439, 2024). "Given the high expression of TRIM69 in CA20-high cancers, we considered the possibility that TRIM69 and MST2 may also have roles in promoting centrosome clustering and averting mitotic defects that can arise from multipolar spindles." (PMID 37739411, 2023). "TRIM69-ablation in cancer cells leads to centrosome scattering and chromosome segregation defects." (PMID 37739411, 2023). "We observe that TRIM69 evokes, through degrading EYA4, nuclear β-catenin accumulation and transcription of Id2 gene, which had been reported to favor cancer progression via fostering mitosis, stem cell self-renewal and angiogenesis." (PMID 36741265, 2023). "Based on data from TCGA, comparison of TRIM69 expression in COAD tissues and non-cancer tissues revealed that the level of TRIM69 expression in COAD was significantly lower than that in non-cancer tissues (p < 0.05)." (PMID 37653392, 2023). "Although TRIM69 transcription has not yet been reported to play a role in cancer, the presence of recurrent TRIM69 amplification involving escape from mitotic catastrophe-induced death in Kras cancer strongly suggests that TRIM69 has pro-tumorigenic capacity." (PMID 36741265, 2023). "Additionally, we show that the TRIM69 promotes centrosome clustering through PRC1 and DYNEIN in cancer cells." (PMID 37739411, 2023). "Notably, TRIM69 expression showed significant negative correlations with the IC50 values of various anti-cancer drugs, including 5-fluorouracil, AT-7519, CAL-101, and indisulam." (PMID 37653392, 2023). "Therefore, TRIM69 may serve as a marker of COAD and provide an adjuvant mechanism to enhance the effectiveness of various anti-cancer chemotherapeutic agents, such as 5-fluorouracil and programmed cell death protein 1 (PD-1) inhibitors." (PMID 37653392, 2023).